CCNE1 (cyclin E1)
Diseases named in the same sentence as CCNE1 in open-access papers (continued):
Sharing a sentence is not in itself a finding about the gene and the disease.
glioma (continued). "In this way, to attain the potential molecular mechanisms by which CUL7 promotes glioma development, we detected the expression changes of some key mediators of cell proliferation and apoptosis, including p21, p27, cyclin D1, CDK4, cyclin E1 and CDK2." (PMID 32252802, 2020). "In this study, 47.6% of glioma patients were detected ctDNA including 1p/19q, MDM2, ERBB2, IDH1, CDKN2A, CDK4, PDGFRA, CCNE1, MET." (PMID 32973641, 2020). "Fibronectin, Rad51, Cyclin-E1 and Progesterone Receptor are also shown, along with supporting box plots from the IDH-wt grade II/III glioma vs GBM expression data, and demonstrated higher expression in the PN and GBM samples." (PMID 29142297, 2017). "Here, our study indicates that URGCP promotes glioma growth through upregulating Cyclin D1 and Cyclin E1 expression, and the NF-κB/c-myc/miR-16 pathway is involved in URGCP-mediated Cyclin D1 and Cyclin E1 overexpression in glioma." (PMID 29044221, 2017). "miR-195 inhibits glioma cell proliferation by downregulating expression of Cyclin D1 and cyclin E1, through directly targeting the 3′-UTR of Cyclin D1 and cyclin E1." (PMID 24995320, 2014). "In this investigation, we examined key cell growth regulators and observed that Cyclin D1, Cyclin E1, pRb, and NF-κB were downregulated after stable ENO1 knockdown in glioma U251 and U87 cells." (PMID 24650096, 2014). "Mechanistic analyses revealed that Cyclin D1, Cyclin E1, pRb, and NF-κB were downregulated after stable ENO1 knockdown in glioma U251 and U87 cells." (PMID 24650096, 2014). "As predicted, upregulation of miR-195 decreased, but inhibition of miR-195 increased, the expression levels of cyclin D1 and cyclin E1 in LN18 and T98G glioma cells." (PMID 23383003, 2013). "Glioma-related ctDNAs included 1p/19q, MDM2, ERBB2, IDH1, CDKN2A, CDK4, PDGFRA, CCNE1, MET." (PMID 32973641, 2020). "Moreover, the ctDNAs in the metastatic brain tumors included ALK and MDM2, and glioma-related ctDNAs included 1p/19q and MDM2 followed by frequencies of ERBB2, IDH1, CDKN2A, CDK4, PDGFRA, CCNE1, MET." (PMID 32973641, 2020). "Mechanically, URGCP repressed miR-16 expression via activating NF-κB/c-myc pathway in glioma; Cyclins D1 and Cyclin E1 were identified as the direct targets of miR-16, thus, URGCP-mediated miR-16 downregulation accelerated cell proliferation by upregulating Cyclin D1 and Cyclin E1 expression." (PMID 29044221, 2017). "Moreover, we demonstrated that upregulation of miR-195 in glioma cells led to the downregulation of phosphorylated pRb and proliferative marker PCNA through downregulation of cyclin D1 and cyclin E1 via directly targeting the 3′-UTR of cyclin D1 and cyclin E1." (PMID 23383003, 2013). "To investigate whether URGCP regulates the expression of these regulators in glioma, we performed western blotting and found that silencing URGCP only suppressed Cyclin D1 and Cyclin E1 expression, while, URGCP overexpression enhanced Cyclin D1 and Cyclin E1 expression in U87 and U251 cells." (PMID 29044221, 2017). "As predicted, re-introduction of the Cyclin D1 or Cyclin E1 ORF (without 3′UTR) in miR-195-transfected cells abrogated, at least partially, the miR-195-mediated glioma cell growth arrest, as analyzed by the BrdUrd incorporation assay." (PMID 23383003, 2013).
bladder cancer (33 papers, 2013 to 2025). "In the CCNE1 locus, the original GWAS-identified SNP rs8102137 and a CCNE1 promoter variant rs7257330 were found to be associated with bladder cancer aggressiveness, marked by increased CCNE1 protein expression." (PMID 29956121, 2018). "Moreover, genes such as NAT2, TP63, GSTM1, MYC, TACC3‐FGFR3, PSCA, CLPTM1L‐TERT, APOBEC3A‐CBX6, UGT1A, and CCNE1 get mutated in bladder cancer." (PMID 40755497, 2025). "Studies have suggested that metformin targets the YAP1-TEAD4 complex via AMPKα, regulating the expression of CCNE1/2 (Cyclin E) in bladder cancer cells, inducing cell-cycle arrest and ultimately affecting cell growth." (PMID 40635786, 2025). "Transcriptional control of CCNE1 regulates the cell cycle in bladder cancer, so its aberrant expression leads to rapid proliferation and genomic instability." (PMID 36430344, 2022). "For example, KLF5 binds to a CCNE1 promoter proximal element in bladder cancer cells and KLF5 increases the expression of Ccnb1 and Mcm2 downstream of oncogenic Ras in fibroblasts." (PMID 32880368, 2020). "We show here SPOP interacts with CYCLIN E1, selectively regulates its stability in prostate and bladder cancer cell lines, and regulates PCa tumorigenesis through CYCLIN E1 degradation." (PMID 30237511, 2019). "In summary, our study reveals that MNX1 upregulation plays an important role in bladder cancer progression and that it is a critical cell cycle promoter that upregulates CCNE1 and CCNE2 directly." (PMID 30012177, 2018). "In our GSEA, we not only validated one SNP at CCNE1 from previous GWAS, but also highlighted several novel SNPs, genes, and pathways potentially involved in bladder cancer tumorigenesis." (PMID 27738493, 2016). "In particular, the expression of Cyclin E1 has been correlated with more advanced and invasive bladder cancer, as well as poor clinical outcomes." (PMID 27738493, 2016). "Mechanistically, WDR5 regulated various functions in bladder cancer by mediating the transcription of cyclin B1, cyclin E1, cyclin E2, UHMK1, MCL1, BIRC3 and Nanog by histone H3 lysine 4 trimethylation." (PMID 25656485, 2015). "In addition, it has been demonstrated that MNX1 induces bladder cancer proliferation and tumorigenicity by targeting promoters to upregulate CCNE1 and CCNE2 expression." (PMID 36316768, 2022). "Cycle arrest at G0/G1 transition in human bladder cancer cells may have been due to the enhanced of expression of p21 with a decrease in cyclin E1, CDK2, and CDK4 kinase levels." (PMID 31024833, 2019). "Furthermore, we found that MNX1 can accelerate G1–S transition in the bladder cancer cell cycle by transcriptionally upregulating CCNE1 and CCNE2 expression." (PMID 30012177, 2018). "In conclusion, we believe that these five target genes (GSK3B, CDC20, TPX2, AURKA and CCNE1) may promote the occurrence of bladder cancer and lead to poor prognosis.We explored the potential therapeutic targets of aspirin for bladder cancer by comprehensive bioinformatics analysis." (PMID 36316768, 2022). "CCNE1 amplification was observed frequently in ERBB2amp GEC (21.3%) and bladder cancer (16.7%) and less commonly in other tumors." (PMID 40178042, 2025). "The pathway view of genes frequently altered in bladder carcinoma generated by TCGA1 coheres with this observation, as both CDKN1A and FBXW7 are listed as negative regulators of CCNE1 and cell cycle progression." (PMID 31253832, 2019). "Herein, we investigated that MNX1 upregulates CCNE1 and CCNE2 expression to induce proliferation and tumorigenicity in bladder cancer by targeting their promoters." (PMID 30012177, 2018). "As expected, luciferase reporter assays revealed that MNX1 overexpression activated the luciferase activity of CCNE1 and CCNE2 promoters in the bladder cancer cells, whereas MNX1 downregulation attenuated it." (PMID 30012177, 2018).
bladder cancer (continued). "These together suggest that the regulation of CYCLIN E1 stability by SPOP is cell line specific, and may be selectively occurs in some types of prostate and bladder cancer cell lines." (PMID 30237511, 2019). "In addition, MNX1 transcriptionally upregulated CCNE1 and CCNE2 by directly bounding to their promoters, which promoted G1–S transition in the bladder cancer cells." (PMID 30012177, 2018). "Gene amplification is one of the mechanisms underlying the activation of proto-oncogenes such as ERBB2, CCND1, CCNE1, MDM2, and E2F3, which have been suggested as cancer driver genes in bladder cancers, based on their aberrant gene amplification and protein overexpression." (PMID 27902773, 2016). "For instance, hsa_circ_0014130 works as a sponge of miR-132-3p to advance the oncogenesis and metastasis of bladder cancer by regulating KCNJ12 expression, and circAGFG1 acts as a sponge of miR-195-5p to promote triple-negative breast cancer progression by regulating CCNE1 expression." (PMID 35559038, 2022).
endometrial cancer (32 papers, 2012 to 2025). Primary or metastatic malignant neoplasm involving the endometrium (mucous membrane that lines the endometrial cavity). "Another subset of CNH endometrial cancer characterized by amplification in CCNE1 is also implicated in poor prognostic CNH EC." (PMID 41340866, 2025). "For example, the cell cycle progression gene CCNE1 was both differentially expressed and implicated in patient survival in breast and endometrial cancer." (PMID 37345032, 2023). "CCNE1, the gene encoding cyclin E1 protein, has been observed to be overexpressed in many cancers, including endometrial cancer, which results in chromosome instability." (PMID 37109350, 2023). "Our objective was to establish both the histological and molecular landscape of endometrial cancers in this population, and to confirm whether CCNE1 amplification is specifically associated with the over-represented high-grade subgroups." (PMID 41257933, 2025). "Studies in other cancer types, including serous ovarian cancers and endometrial carcinomas, also showed that CCNE1 amplification or Cyclin E overexpression was associated with more aggressive tumor features, but was not an independent predictor factor of survival." (PMID 32964114, 2020). "We show that these focal deletions occur in the context of cyclin E1 amplification in breast, ovarian, and endometrial cancers, and serve to disrupt BRD4 regulatory regions and gene expression across isoforms." (PMID 40112818, 2025). "In vitro and in vivo studies have reported sensitivity of UCS cell lines to the ATR inhibitor elimusertib, and a separate study has reported synergy between Wee1 and ATR inhibition in CCNE1-amplified ovarian and endometrial cancer models." (PMID 40678577, 2025). "This pattern is consistent with prior findings linking CCNE1 overexpression to genomic instability and aggressive behavior in endometrial cancer." (PMID 41331376, 2025). "In the present cohort of 55 newly diagnosed endometrial carcinomas, CCNE1 status was assessed exclusively by dPCR." (PMID 41257933, 2025). "The identification of CCNE1 amplification, which is currently being explored as a therapeutic target in clinical trials, suggests new treatment strategies for high-grade endometrial cancer." (PMID 38564163, 2024). "CCNE1 amplification has been reported in breast, ovary, gastric, and endometrial cancers and was related to poor prognosis." (PMID 37131253, 2023). "In ovarian and endometrial cancer models, animal group with CCNE1 amplification had much longer survival rate than the CCNE1 low group." (PMID 35458687, 2022). "Although prior studies have reported that CCNE1 amplification is associated with poor prognosis in endometrial cancer, we did not observe an increased risk of death or recurrence in this cohort." (PMID 41340866, 2025). "Ovarian and endometrial cancers with CCNE1-amplification are often resistant to standard treatment." (PMID 40169546, 2025). "Therefore, CCNE1 amplification is a biomarker for the application of WEE1 inhibitors in endometrial cancer." (PMID 37109350, 2023). "Amplification of CCNE1/URI predominantly occurred in type II endometrial cancer." (PMID 27582547, 2017).
endometrial cancer (continued). "Despite these limitations, this study leverages a large, well-characterized cohort with comprehensive genomic profiling, enabling detailed evaluation of CNH endometrial cancers and MECOM, CCNE1, and ERBB2 gene amplifications." (PMID 41340866, 2025). "The objective of this study was to characterize a novel subset of CNH endometrial cancer, MECOM amplified, and to examine the overlap of MECOM amplification with amplification in CCNE1 and ERBB2 using a publicly available dataset." (PMID 41340866, 2025). "Despite the broad role of CDK2 in the cell cycle, only cluster 3, largely comprising of ovarian and endometrial cancer cell lines, exhibited exclusive vulnerability to CDK2 and CCNE1 depletion." (PMID 39924553, 2025). "CCNE1 was amplified in 7.6 % (40/523) of the tumors in the cohort, of which 97.5 % (39/40) were found in CNH endometrial cancer." (PMID 41340866, 2025). "For example, endometrial cancer is characterized by intrachromosomal amplification of ESR1, KRAS, PIK3CA, ERBB2, TERC, MYC, CCNE1." (PMID 41415205, 2025). "Survival analysis showed that the higher the expression levels of lncRNAs C2orf48, PSAT1, KIF23, CCNE1, CDC25A and CBX2 in patients with endometrial cancer, the poorer the prognosis." (PMID 30581678, 2018). "In endometrial cancer, patients with carcinosarcoma, serous adenocarcinoma and leiomyosarcoma showed many alterations of cancer driver genes, such as MYC and CCNE1." (PMID 30046040, 2018). "Notably, MECOM amplification co-occurred with CCNE1 and ERBB2, two subsets of endometrial cancer known for their poor prognosis in CNH tumors." (PMID 41340866, 2025). "We similarly observed an increase in the mean CCNE1 copy number when considering only breast, ovarian, and endometrial cancers with and without a BRD4 focal deletion (7.1 vs. 4.1; p = 0.0002; Wilcoxon rank-sum test)." (PMID 40112818, 2025). "Prospective clinical trials are warranted to assess the utility of combined 19q12 amplification and Cyclin E1/URI protein expression analysis for the prediction of therapeutic response to chemotherapy and/or cyclin-dependent kinase inhibitors in patients with endometrial cancer." (PMID 27582547, 2017). "Furthermore, even in the absence of co-amplification of CCNE1 or ERBB2, MECOM amplification alone conferred a similar two-fold increase in risk, suggesting that MECOM amplification may independently identify an aggressive subset of endometrial cancers." (PMID 41340866, 2025).
triple-negative breast carcinoma (28 papers, 2017 to 2025). An invasive breast carcinoma which is negative for expression of estrogen receptor (ER), progesterone receptor (PR), and human epidermal growth factor receptor 2 (HER2). "Pt#71 also presented an amplification in CCNE1 (Cyclin E1) gene, which is known to be associated with poor prognosis in ovarian and triple-negative breast cancer, probably involved in the emergence of resistance to chemotherapy." (PMID 34178989, 2021). "Previous study by Asghar U indicated that a subset of triple-negative breast cancer cells with expression of AR and the loss of cyclin E1 could be responsive to CDK4/6 inhibition." (PMID 28438180, 2017). "However, levels and activity of miR-195 were recently shown to be also dependent on a sponging circular RNA, circAGFG1, in triple-negative breast cancer; of note, circAGFG1 is able to cause Cyclin E1 (CCNE1) upregulation as a consequence of miR-195 sequestering." (PMID 32626702, 2020). "Based on previous reports of the cGAS/STING pathway being highly expressed and coupled to immune cell infiltration in triple-negative breast cancer with replication stress, we explored the expression of cyclin E1, cyclin D1 and c-Myc and immune infiltration." (PMID 39751944, 2025). "For example, circRNA circAGFG1 serves as a sponge of miR-195-5p to promote triple-negative breast cancer progression through regulating cyclin E1 expression." (PMID 33735323, 2021). "CircAGFG1 promotes triple-negative breast cancer progression through the circAGFG1/miR-195/CCNE1 pathway." (PMID 33718161, 2021). "The circRNA circAGFG1 exerts oncogenic effects by sponging miR-195-5p, which modulates cyclin E1 expression and promotes tumorigenesis and the development of triple-negative breast cancer." (PMID 31576812, 2019). "Some studies have suggested that miR-497-5p could inhibit the proliferation and invasion of triple-negative breast cancer cells by targeting CCNE1, block the cell cycle and promote cell apoptosis." (PMID 35419295, 2022). "Moreover, HR+/HER2- and basal-like tumors are biologically more similar to triple-negative breast cancers, characterized by increased expression of cyclin E1, EGFR, and p16 and low expression of ER1, PGR1, and Forkhead box1." (PMID 35806079, 2022). "Moreover, it was reported that circAGFG1, which was significantly upregulated in triple-negative breast cancer, promotes tumor growth and metastasis by upregulating the downstream oncogene CCNE1." (PMID 32386516, 2020). "Cyclin E1 (CCNE1) plays an important role in the G1/S phase transition of the cell cycle and has been found to play an oncogenic role in many cancers, such as triple-negative breast cancer, epithelial ovarian cancer, and liver cancer." (PMID 36292952, 2022).